TET1 (tet methylcytosine dioxygenase 1)
Diseases named in the same sentence as TET1 in open-access papers (continued):
Sharing a sentence is not in itself a finding about the gene and the disease.
asthma (16 papers, 2016 to 2025). "Hypomethylation of the TET1 gene (located at 10q21.3) in the nasal epithelium has been associated with the development of asthma in children exposed to traffic-related air pollution." (PMID 41008562, 2025). "IL-33 and Th17 cytokines have been mechanistically linked to TET1-mediated promoter demethylation in asthma models." (PMID 41020825, 2025). "This suggests a mechanistic explanation for the exacerbated asthma-like phenotype in TET1-deficient mice following HDM treatment." (PMID 38168374, 2023). "Collectively, our analyses reveal a new link between TET1, CTCF and enhancers that future studies should expand on to improve our understanding of the role of TET1 in responding to environmental exposures linked to asthma." (PMID 38168374, 2023). "IL1B, a major stimulator of the acute phase response pathway that has been linked to asthma, showed increased gene expression following both TET1 loss and HDM treatment." (PMID 38168374, 2023). "Among the first potential biomarkers in nasal epithelial cells proposed for asthma was TET1 as the hypomethylation of its promoter was associated with childhood asthma in African Americans." (PMID 35344303, 2022). "The study revealed the loss of methylation at a single CpG site in the TET1 gene promoter and increased global 5‐hmC levels which were significantly associated with asthma." (PMID 34754417, 2021). "5-Hydroxymethylcytosine (5-hmC) and TET1 expression are known to be associated with in-house dust mite-induced asthma in the lungs of mouse models." (PMID 31470889, 2019). "Asthma was significantly associated with loss of methylation at a single CpG site in the TET1 promoter (cg23602092) and increased global 5hmC in bronchial epithelial cells and human participants." (PMID 32047643, 2019). "Loss of methylation at a single CpG site in the TET1 promoter and increased global 5-hmC levels were significantly associated with asthma." (PMID 31470889, 2019). "In the HDM-challenged mouse model, we observed an increase in the Th2 response in the absence of Tet1, while the IFN signaling pathway negatively regulated by Tet1 is mostly involved in viral responses and has been linked to asthma severity and exacerbation." (PMID 31089182, 2019). "Methylation of the TET1 promoter in nasal cells has been associated with severe asthma in children." (PMID 38168374, 2023). "Previous studies have identified TET1 as a potential key regulator of genes linked to asthma." (PMID 38168374, 2023). "TET1 has been shown to transcriptionally respond to house dust mite extract, an allergen known to directly cause allergic asthma development, and regulate the expression of genes involved in asthma." (PMID 38168374, 2023). "Therefore, we searched for the presence of asthma-associated variations in DNA methylation and histone acetylation found in airway epithelial cells among TET1-loss induced differentially accessible regions and DMRs." (PMID 38168374, 2023). "From example, the loss of DNA methylation in one CpG site in the promoter region of TET1 was associated with air pollution and childhood asthma and could possibly be a potential biomarker for childhood asthma." (PMID 28191262, 2017). "Recent evidence from our group associated lower TET1 promoter methylation and higher 5hmC levels in airway epithelial cells with childhood asthma, uncovering a novel role of TET1 and DNA demethylation in asthma development." (PMID 27777592, 2016). "Methyl-CpG-binding domain protein 2 (MBD2), a “reader” protein, recognizes methylated CpG sites, while the DNA demethylating enzyme TET1 functions as an “eraser” in asthma." (PMID 41008562, 2025). "A study using a mouse model of house dust mite–induced asthma reported an altered methylome, elevated levels of 5-hydroxymethylcytosine (5-hmC), and increased TET1 expression in the lungs, suggesting a potential role for TET1 in the pathogenesis of asthma." (PMID 41008562, 2025).
asthma (continued). "Overall, our data shed light on how TET1 regulates critical pathways involved in asthma and response to allergens." (PMID 38168374, 2023). "Loss of TET1 and HDM treatment lead to similar changes in H3K27ac, and these changes are enriched for asthma-associated changes in H3K27ac." (PMID 38168374, 2023). "Understanding how TET1 regulates expression to contribute to allergic responses and asthma development thus requires a comprehensive approach." (PMID 38168374, 2023). "Our genome-scale data analyses indicate that reduction of TET1, a key regulator of asthma, in human bronchial epithelial cells leads to global changes in chromatin accessibility, DNA methylation, H3K27ac, and gene expression." (PMID 38168374, 2023). "In particular, our previous studies indicate that Ten-eleven translocation methylcytosine dioxygenase 1 (TET1) is a key epigenetic modulator in asthma." (PMID 38168374, 2023). "Collectively, our data suggest novel molecular mechanisms through which TET1 regulates critical pathways following allergen challenges and contributes to the development of asthma." (PMID 38168374, 2023). "As chronic airway inflammation induced by allergens plays a critical role in the pathophysiology of asthma, these novel findings support that Tet1 is a potential therapeutic target of asthma." (PMID 35627266, 2022). "Meanwhile, there were five different genes that were consistently downregulated in ciliated cells following Tet1 loss and/or HDM treatment, including the asthma-associated genes Gstp1, Gstm1, and Gpx2." (PMID 35627266, 2022). "Several of these DEGs associated with Tet1 loss in AT2 cells (Il33, Areg and Bpifa1, Hspa8 and Lgals3 (also DEGs in ciliated cells)), have been previously linked to asthma." (PMID 35627266, 2022). "To determine the role of Tet1 in asthma development, we utilized an experimental model of allergic airway inflammation that was previously established." (PMID 31089182, 2019). "The expression of TET1 is regulated by asthma-related exposures such as diesel exhaust particles and house dust mite (HDM) in human bronchial epithelial cells and in whole lungs of mice." (PMID 31089182, 2019). "A cohort of African American children was found to be at higher risk of developing asthma, after exposure to TRAP when a 5’-C-phosphate-G-3’(CpG) site in the TET1 promoter was methylated." (PMID 31703266, 2019). "Recently we found that TET1 promoter methylation is associated with both TRAP exposure and asthma prevalence in children." (PMID 27777592, 2016). "A few recent reports have demonstrated the regulatory role of TET1/2/3 in hematopoiesis, B cell lineage specification and Treg differentiation, which are all involved in asthma development." (PMID 27777592, 2016). "In addition, TET1 regulates the expression of genes involved in asthma to protect against allergic asthma." (PMID 38168374, 2023). "TET1 knockdown and HDM treatment have each individually been linked to asthma." (PMID 38168374, 2023). "AHR activation in some immune cells favors the anti-inflammatory phenotype, and AHR-related epigenetic regulation involving the ten-eleven translocation 1 (TET1) methylation alleviates interferon activation, protecting bronchial epithelial cells against asthma features." (PMID 34576152, 2021). "As TET1 can be modulated by small molecules (vitamin C, L-cysteine, 2-HG, etc) and miRNAs34, our findings may promote the development of new asthma therapies." (PMID 31089182, 2019). "In conclusion, we identified a novel role for Tet1 in asthma development." (PMID 31089182, 2019). "Notably, TET1 promotes IL-4 expression by demethylating its promoter, contributing to allergic airway inflammation, thereby linking its structural domains directly to immune dysregulation in asthma." (PMID 41008562, 2025). "Therefore, our studies suggest that these exposures may contribute to asthma through the function of Tet1 on gene regulation." (PMID 31089182, 2019).
asthma (continued). "Another study from the same group demonstrated in turn that DNA methylation at the TET methylcytosine dioxygenase 1 gene (TET1) contributes to traffic-related air pollution and asthma." (PMID 32973742, 2020). "However, the contributions of TET1 to asthma remain unknown." (PMID 31089182, 2019). "Functional studies directly assessing the interplay between TET1, histone modifications, CTCF binding and gene expression could prove fruitful for understanding the role of TET1 in responding to environmental exposures and regulating asthma." (PMID 38168374, 2023). "Therefore, our data support that TET1-mediated chromatin accessibility might influence H3K27ac marks and cis-regulatory elements and CTCF binding to regulate gene expression, which may explain its role in protection from inflammation and asthma." (PMID 38168374, 2023).
endometrial cancer (16 papers, 2018 to 2024). Primary or metastatic malignant neoplasm involving the endometrium (mucous membrane that lines the endometrial cavity). "Downregulation of TET1 gene and protein expression, could be associated with the abnormal inactivation of ERα and PR seen in endometrial cancer tissues." (PMID 35372016, 2022). "Limited evidence suggests the involvement of TET (Ten Eleven Translocation)-mediated DNA hydroxymethylation in endometrial cancer, with some data on the use of TET1 as a potential prognostic and diagnostic biomarker, however the mechanisms guiding it and its regulation remains unexplored." (PMID 35372016, 2022). "Prior studies have highlighted TET1’s role in driving the proliferation of insulin-dependent endometrial cancer by enhancing G protein-coupled estrogen receptor expression and PI3K/AKT pathway activation." (PMID 39104395, 2024). "Based on obtained results, the authors have proven that the level of TET1 gene expression is an independent prognostic factor of survival in endometrial cancer." (PMID 35409163, 2022). "Data by other studies report similar findings with decreased TET1 mRNA and protein expression in endometrial cancer tissues compared to normal." (PMID 35372016, 2022). "This is also consistent with findings in other endometrial cancer cells that suggest, TET1 increases estrogen sensitivity by upregulating mRNA expression of orphan nuclear receptor - GPER, in ishikawa and HEC-1-A cells." (PMID 35372016, 2022). "mRNA and Protein upregulation of TET1 is also demonstrated in another study suggesting that the hypoxic, chronic inflammatory environment seen in endometrial cancer, can up-regulate TET1 expression and induce its downstream gene transcription." (PMID 35372016, 2022). "Although previously published research article has reported that TET1 mRNA expression and correlated 5-hmC levels are reduced in endometrial cancer tissues." (PMID 34731191, 2021). "TET1-MUT is also more frequently detected in endometrial cancer and gastrointestinal cancer, as well as lung and skin cancers." (PMID 31623662, 2019). "Moreover, TET1 was also found as the upstream regulator of GPER expression in endometrial cancer cells." (PMID 39201247, 2024). "Metformin (N,N-dimethylbiguanide), a potent anti-diabetic molecule also used in cancer treatment for its anti-tumorigenic properties, sensitizes endometrial cancer to progestin by targeting Tet methylcytosine dioxygenase 1 (TET1), which downregulates Glo1 expression." (PMID 33869040, 2021). "In addition, endogenous levels of TET1 appears to influence responsiveness of endometrial cancer cells to progestin as Metformin has been shown to downregulate TET1’s expression as well as sensitize endometrial cancer cells to progestin." (PMID 31426393, 2019). "Thus, the role of TET3 in endometrial cancer seems to be different than TET1 or TET2, and this protein may be involved in modifications of histones by targeting other proteins to chromatin." (PMID 34948036, 2021). "Moreover, decreased TET1 expression correlates with tumor progression and may serve as a potential prognostic biomarker in endometrial cancer." (PMID 29849955, 2018). "The data obtained from this study indicates that the downregulation of TET1 in response to estrogen and progesterone could potentially be contributing to epigenetic deregulation and warrants the need for more studies to investigate its role in endometrial cancer." (PMID 35372016, 2022). "For example, a higher level of TET3 and lower levels of TET1 and TET2 were found in endometrial cancer compared with the normal endometrium, whereas endometrial cancer tissues showed lower levels of global hydroxymethylation at the same time." (PMID 36685517, 2022). "Our previous studies showed that TET1 and TET2 messenger RNA expression was lower and TET3 expression was higher in endometrial cancers compared to normal tissues." (PMID 34948036, 2021).
endometrial cancer (continued). "Insulin upregulates TET1 and then upregulates GPER expression, which enhances the sensitivity of endometrial cancer cells to estrogen." (PMID 31440472, 2019). "It has been reported that M2 macrophages infiltrated in the microenvironment of endometrial cancer can enhance the sensitivity of endometrial cancer cells to estrogen by releasing cytokine IL17A and upregulating the expression of ERα through TET1-mediated epigenetics." (PMID 31440472, 2019). "Moreover, lower TET1 and TET2 expression has been reported in the cases of endometrial cancer." (PMID 37576599, 2023). "The levels of TET1 and TET2 (but not TET3) have been shown to be reduced in endometrial cancer as compared to matching normal, and reduced levels of TET1/2 correlate with reduced levels of 5-hmC and increased tumor aggressiveness." (PMID 31426393, 2019). "As obesity and insulin resistance are commonly found in patients with endometrial cancer, a recent report suggests a role of increased non-genomic GPER signaling in endometrial cancer cells through TET1 upregulation in tumor microenvironment, through a yet, to-be defined mechanism." (PMID 31426393, 2019).
bladder cancer (15 papers, 2018 to 2025). "In cancer, TET1 has been associated with various solid tumors, including breast and bladder cancer (as discussed in this review), while TET2 is frequently mutated in hematological malignancies." (PMID 40520993, 2025). "Currently, the role of TET1 in the development of urinary bladder cancer (UBC) and its underlying molecular mechanisms remain unclear." (PMID 32528872, 2020). "TET1 expression was recently reported to be associated with apoptosis in bladder cancer cells." (PMID 30988069, 2019). "POU5F1 can enhance tumour immune response by upregulating the TET1-dependent NRF2/MDM2 axis in bladder cancer." (PMID 36685927, 2022). "The association between ten-eleven translocation 1 (TET1) protein levels and clinicopathological features of urinary bladder cancer (UBC) patients." (PMID 32528872, 2020). "Another study by Mao et al29 suggested that OCT3/4 may promote tumor immune evasion in bladder cancer by enhancing the TET1–nuclear factor erythroid 2-related factor 2 (NRF2)–MDM2 pathway." (PMID 40520993, 2025). "The involvement of TET1 in bladder cancer progression is an area of growing interest." (PMID 40520993, 2025). "Subsequent step-wise multivariate regression distilled the model to four independent predictors—NPM1 (HR = 1.42), RUNX2 (HR = 1.25), TET1 (HR = 1.41), and TIA1 (HR = 0.67)—thereby establishing a concise LLPS-related signature for risk stratification in bladder cancer." (PMID 41300366, 2025). "In addition to TET1, our study also identified mutations affecting the E3 ubiquitin-protein ligase RNF43 as a potential predictor of therapeutic responses, notably for colorectal and bladder cancer patients." (PMID 35798829, 2022). "-The TET1/USP28/CD44/RhoGDIβ pathway was identified as the regulator of the oncogenic activities of ATG7 for stem-like property, invasion, and lung metastasis of human bladder cancer cells." (PMID 35269796, 2022). "In addition, the silencing of TET1 reduced 5hmC levels and promoted cell proliferation by down-regulating the expression of AJAP1 in bladder cancer cells." (PMID 34852853, 2021).
acute lymphoblastic leukemia (13 papers, 2013 to 2025). Leukemia with an acute onset, characterized by the presence of lymphoblasts in the bone marrow and the peripheral blood. "TET1 expression is frequently deregulated in solid tumors, but a prominent role in the regulation of B-cell malignancies has been demonstrated, and evidence of its mutations exists in T-acute lymphoblastic leukemia." (PMID 29069286, 2018). "The ATM (ATM Serine/Threonine Kinase) inhibitor (AZD0156) and staurosporine inhibit the phosphorylation of TET1 (tet methylcysteine dioxygenase 1), causing instability of the TET1 protein and demonstrating a synergistic killing effect on B-ALL (B cell acute lymphoblastic leukemia) cells." (PMID 38474445, 2024). "Interestingly, auranofin induces cell death of T cell acute lymphoblastic leukemia by inhibiting dioxygenases TET1 instead of TrxR." (PMID 41392982, 2025). "Analysis of public datasets (GSE5820) revealed that TET1 expression is elevated in patients with T-cell acute lymphoblastic leukemia (T-ALL) and serves as a biomarker for decreased survival." (PMID 40076706, 2025). "In contrast, TET1 can also act as an oncogene during leukemogenesis, particularly in T-cell acute lymphoblastic leukemia (T-ALL)." (PMID 36675240, 2023). "Interestingly, high expression of TET1 leads to global hydroxymethylation in T-cell acute lymphoblastic leukemia (T-ALL), which protects cells from DNA damage and thereby promoting leukemic growth." (PMID 34957093, 2021). "Here, we report that in T cell acute lymphoblastic leukemia (T-ALL) the MYC oncogene controls the expression of TET1 and TET2 to maintain 5-methylcytosine (5mC) and 5-hydroxymethylcytosine (5hmC) patterns, which is associated with tumor cell-specific gene expression." (PMID 31266538, 2019).